CD44 (CD44 molecule (IN blood group))
Diseases named in the same sentence as CD44 in open-access papers (continued):
Sharing a sentence is not in itself a finding about the gene and the disease.
Hereditary breast cancer (2 papers, 2008 to 2009). Breast carcinoma that has developed in relatives of patients with history of breast carcinoma. "We demonstrate an association between basal-like and particularly BRCA1 hereditary breast cancer and the presence of CD44+/CD24- cells." (PMID 18559090, 2008).
Hypertension (2 papers, 2013 to 2021). The presence of chronic increased pressure in the systemic arterial system. "In addition, it has been observed that Ang II-induced infiltration of T cells into the blood vessels during hypertension involves increases in CD44 and CCR5." (PMID 23646169, 2013).
hypothyroidism (2 papers, 2013 to 2020). Abnormally low levels of thyroid hormone. "After PPI network construction, the top five hub genes associated with hypothyroidism were extracted, including ALB, MAPK1, SPP1, PPARG, and MIF, whereas those associated with hyperthyroidism were ALB, FCGR2B, CD44, LCN2, and CD74." (PMID 32500465, 2020). "The top five hub genes associated with hypothyroidism are ALB, MAPK1, SPP1, PPARG, and MIF, whereas those associated with hyperthyroidism are ALB, FCGR2B, CD44, LCN2, and CD74." (PMID 32500465, 2020).
immune deficiency (2 papers, 2020 to 2025). "Downregulated genes in CD69+ CD4+ T cells were involved in cell adhesion (PTPRC; -0.38log2FC), differentiation (CD44; -0.38log2FC), and immunodeficiency (IL7R; -0.42log2FC) pathways." (PMID 41208955, 2025).
laryngeal squamous cell carcinoma (2 papers, 2013 to 2023). A squamous cell carcinoma that arises from the larynx. "In tumors from stratified epithelium, irregular and locally reduced staining of hyaluronan and CD44 in the primary tumor associated with high frequency of metastasis in laryngeal squamous cell carcinoma." (PMID 23560496, 2013). "We focus on the new prognostic and predictive factors CD44, PDL1, and ATG7 in our study of surgical samples of patients with laryngeal squamous cell carcinoma (LSCC) using tissue microarray (TMA)." (PMID 37173926, 2023). "Here, we highlight the discovery of new prognostic and predictive factors, CD44, PDL1, and ATG7, from our study of surgical samples of patients with laryngeal squamous cell carcinoma (SCC) using tissue microarray (TMA)." (PMID 37173926, 2023). "We are going to highlight new prognostic and predictive factors, CD44, PDL1, and ATG7, in surgical samples from patients with laryngeal squamous cell carcinoma (LSCC)." (PMID 37173926, 2023).
leiomyosarcoma (2 papers, 2021 to 2023). An uncommon, aggressive malignant smooth muscle neoplasm, usually occurring in post-menopausal women. "Many CD44-positive cells were found in the internal tissue of intravenous leiomyomatosis and the internal tissue of intravenous uterine leiomyosarcoma." (PMID 34563053, 2021). "CD44-positive mesenchymal tumor stem-like cells were detected in both patients with intravenous leiomyomatosis and uterine leiomyosarcoma." (PMID 34563053, 2021). "Similar to uterine leiomyosarcoma, many mesenchymal tumor stem-like cells, such as CD44-positive mesenchymal tumor cells, believed to have the ability to infiltrate into the vasculature, were found in intravenous leiomyomatosis tissue." (PMID 34563053, 2021). "The expression status of CD44 was examined at each tissue site of uterine leiomyosarcoma." (PMID 34563053, 2021). "Many CD44-positive cells (i.e., mesenchymal tumor stem-like cells) are found in the internal tissue of intravenous leiomyomatosis, as well as in the internal tissue of intravenous leiomyosarcoma." (PMID 34563053, 2021).
leukopenia (2 papers, 2020 to 2023). "To establish that AFP causes a leukopenia by stimulating WBC death, we isolated PBMCs from P47 Control and Sco1hep mice and cells positive for CD44, a marker of activation, and annexin V, an indicator of cell death." (PMID 36301669, 2023).
lung NETs (2 papers, 2023 to 2025). "Emerging molecular markers, such as protein expression of CD44, ASCL1, and OTP and TERT gene expression have shown prognostic value in lung NETs, alongside traditional markers like Ki-67 and somatostatin receptors." (PMID 40026252, 2025).
mastocytosis (2 papers, 2023). A clonal myeloproliferative neoplasm characterized by the proliferation and accumulation of neoplastic mast cells in one or multiple organs or organ systems. "Expression of CD44 was reported to be regulated by STAT5 activation in mastocytosis, possibly linking cytokine signaling to the expression of CSCs through STAT5 activation." (PMID 36902436, 2023). "This was accompanied by changes in the gene expression of adhesion molecules including CD44 and other molecules known to be chemoattractant molecules and receptors for mast cells such as CXCR4 and CCL2 (or MCP-1) and with reported functions in mastocytosis." (PMID 37025992, 2023).
meningitis (2 papers, 2011 to 2016). A disorder characterized by acute inflammation of the meninges of the brain and/or spinal cord. "The release of P65 and the adhesion molecules ICAM-1 and CD44 into CSF were all augmented by E44 infection and suppressed by both vimentin deficiency and IbeA deletion, which confirmed IbeA-vimentin interaction could aggravate the inflammatory response in E. coli meningitis." (PMID 27657497, 2016). "Proinflammatory cytokines (IL-1β, IL-6, TNFα, MCP-1, MIP-1alpha, and RANTES) and adhesion molecules (CD44 and ICAM-1) were significantly reduced in the cerebrospinal fluids of the α7-/- mice with E. coli meningitis." (PMID 21966399, 2011).
Miscarriage (2 papers, 2013 to 2022). A pregnancy that ends at a stage in which the fetus is incapable of surviving on its own, defined as the spontaneous loss of a fetus before the 22th week of pregnancy. "For instance, the CD44-mediated inchoate attachment between endometrial epithelial cells and trophectoderm and relatively low CD44 expression in decidual cells were found to be associated with unexplained incidences of miscarriage." (PMID 36527033, 2022). "Finally, we compared HA and CD44 expression in DSCs between the normal early pregnancy and unexplained miscarriage." (PMID 24069351, 2013).
mucositis (2 papers, 2018 to 2022). Mucositis is inflammation and damage of the mucous membranes lining the mouth and other parts of the gastrointestinal (GI) tract. "The peri-implantitis group had significantly higher levels of vascular endothelial growth factor (VEGF), CD34, and CD44 expression compared to the other groups (peri-implant health, peri-implant mucositis)." (PMID 35886240, 2022). "This negative feedback of mucositis included mucosal crypt proliferation, regeneration, and anti-apoptosis, assessed by Ki67, CD44, and BAX IHC staining, respectively." (PMID 29867884, 2018).
myocardial ischemia (2 papers, 2022 to 2025). A disorder of cardiac function caused by insufficient blood flow to the muscle tissue of the heart. "Similar to findings in T cells after myocardial ischemia/reperfusion (I/R), monocytes isolated from Has3-deficient mice with AAA displayed reduced CD44 surface expression and impaired migration across an endothelial layer." (PMID 41280888, 2025). "We observed that the expression of CD44 in the border zone of the infarcted heart was tightly related to pathological angiogenesis following myocardial ischemia." (PMID 36463112, 2022). "Previous studies have pointed out that CD44 can regulate the processes of inflammation, fibrosis, and cardiac remodeling after myocardial ischemia, but few studies have demonstrated the relationship between CD44 and angiogenesis following MI." (PMID 36463112, 2022).
myxofibrosarcoma (2 papers, 2022 to 2025). A malignant fibroblastic neoplasm arising from the soft tissue. "A multivariate study focused on the analysis of CD44 isoforms in 34 adult patients with myxofibrosarcoma showed that increased expression of CD44s and reduced expression of CD44v6 isoform correlated significantly with an improved outcome (p<0.05 and p<0.02, respectively)." (PMID 35785191, 2022).
nephrocalcinosis (2 papers, 2018 to 2025). Nephrocalcinosis is a disorder that occurs when too much calcium is deposited in the kidneys. "Nevertheless, nephrocalcinosis does not solely depend on the crystal aggregation, but also on the adhesion of crystals to the luminal side of tubular cells, a process that is enabled by crystal adhesion molecules expressed on the cell surface, e.g., CD44 and annexin II." (PMID 30319631, 2018).
nephropathies (2 papers, 2021 to 2024). "This was consistent with the immunostaining of kidney sections illustrating that CD44 and annexin II were highly expressed in B6N mice with CaOx crystal-induced nephropathy as compared to B6N mice on control diet." (PMID 33968083, 2021). "When compared to conventional markers of disease activity (anti-dsDNA antibody and C3 levels) and kidney damage (proteinuria, serum creatinine and renal SLEDAI-2K score), CD44 level showed a better correlation with eGFR, and comparable correlation with serological and clinical parameters of disease." (PMID 39411720, 2024).
Ovarian cyst (2 papers, 2022 to 2023). The presence of one or more cysts of the ovary. "Our results suggest that endometriotic ovarian cyst specimens exhibit decreased expression of CD44 and OPN in both epithelium and stroma compartments after progestin therapy." (PMID 37509675, 2023). "Previous researchers reported that soluble CD44 is highly expressed in endometriotic cyst fluid in comparison with other ovarian cysts." (PMID 35907907, 2022).
polyp (2 papers, 2024). A usually exophytic mass attached to the underlying tissue by a broad base or a thin stalk. "We further determined the expression levels of CD44, IL8, CXCR2 and c-myc in an independent validation study consisting of rectal swab specimens from 60 normal subjects, 45 CRC subjects and 68 polyp patients." (PMID 38891062, 2024). "For patients with JPS polyps, our study identifies several potential approaches, including anti‐TNF, anti‐CD44 and anti‐VEGF therapies, to reduce polyp recurrence after polypectomy or serve as palliative treatments if polypectomy is not feasible." (PMID 38264936, 2024). "CD44, CXCR2 and c-myc levels showed around a 1.30- to 1.80-fold increase in polyp subjects when compared to normal subjects, whereas the CXCR2 and c-myc levels were around 0.5- to 0.7-fold lower in polyp subjects when compared to those in CRC subjects." (PMID 38891062, 2024).
posterior fossa ependymoma (2 papers, 2020 to 2022). A high grade ependymoma that is located within the posterior fossa. "Furthermore, abnormal activation of the PI3K-Akt pathway was observed in CD44-positive pediatric posterior fossa ependymoma, suggesting CD44 might be involved in the regulation of PI3K-Akt pathway." (PMID 33303029, 2020).
psoriasis plaque (2 papers, 2016 to 2021). "The ratio of CD19+CD44+ B cells in PBMCs frompatients with psoriasis vulgaris at the active stage was upregulated compared withHCs (P<0.01)." (PMID 27532281, 2016). "Our results indicated that CD44 was significantly elevated inPBMCs in patients with psoriasis vulgaris." (PMID 27532281, 2016).
pulmonary arterial hypertension (2 papers, 2025). Pulmonary arterial hypertension (PAH) is a group of diseases characterized by mean pulmonary artery pressure >20 mmHg and elevated pulmonary arterial resistance leading to right heart failure. "Recently, CD44 variants have been linked to the EndMT in the context of pulmonary hypertension." (PMID 40028673, 2025). "By analyzing bulk RNA-seq data from idiopathic pulmonary hypertension (IPAH) patients and conducting single-cell RNA-seq analysis on pulmonary arterial cells, we identified CD44 as a key modulator of inflammation." (PMID 40971695, 2025).
Salmonella Infections (2 papers, 2010 to 2021). Infections with bacteria of the genus SALMONELLA. "Thus, the sharp increase in T cell activation that occurs between weeks 3 and 4 after Salmonella infection is confirmed using both transient (CD25, CD69) and more stable (CD44, CD62L, IFN-γ) markers of T cell activation." (PMID 20714351, 2010). "Given the durability whereby T cells maintain changes in CD44 and CD62L expression, and IFN-γ production after activation, the expression of more transient T cell activation markers such as CD25 and CD69 were also quantified throughout persistent Salmonella infection." (PMID 20714351, 2010). "We characterized the activation and memory state of SFB-induced IL-17A and/or IL-22 producing CD4+ T cells based on the expression of specific markers including CCR6, CD44, and CD62L in the presence or absence of Salmonella infection." (PMID 34566952, 2021).
scrub typhus (2 papers, 2018 to 2022). Scrub typhus is a rare dust mite-borne infectious disease caused by the Orientia tsutsugamushi bacterium and characterized clinically by an eruptive fever which is potentially serious. "It is known that CD44+ activated T cells may contribute to controlling bacterial growth through production of cytokines (e.g. IFN-γ and TNF-α) and granules (granzyme B), and that decreased CD4+ T cell numbers observed in acute scrub typhus patients is likely due to increased cell apoptosis." (PMID 35479068, 2022).
status epilepticus (2 papers, 2022 to 2023). Status epilepticus is defined as a continuous seizure lasting more than 30 min, or two or more seizures without full recovery of consciousness between any of them. "In the present study, CD44 AsKO mice developed fewer spontaneous behavioral seizures following KA-induced status epilepticus than CTRL mice." (PMID 37296604, 2023). "In addition to these roles in immunity, CD44 also functions in axonal pathfinding during development and high levels of expression have been correlated to mossy fiber sprouting after status epilepticus in mice." (PMID 36172274, 2022). "It is possible that astrocytes with increased expression of CD44 upon KA-induced status epilepticus do not buffer glutamate as efficiently as non-reactive astrocytes." (PMID 37296604, 2023).
sympathetic ophthalmia (2 papers, 2022 to 2023). Sympathetic ophthalmia (SO) is a bilateral granulomatous anterior uveitis usually occurring within the three months following trauma or a surgical procedure involving one eye. "Further studies showed that CD44 levels in the iris, ciliary body, choroid, and retina are higher in patients suffering from sympathetic ophthalmia." (PMID 38275380, 2023). "For example, in patients with sympathetic ophthalmia, the expression of VLA-4, VLA-5, VCAM-1, ICAM-1, and CD44 in the peripheral blood was significantly increased in acute inflammation compared to either the disease resolution phase or normal eyes." (PMID 35008929, 2022).
synovitis (2 papers, 2023 to 2025). Inflammation of a synovial membrane. "We hypothesized that A) CD44 genetic ablation protected against development of synovitis in vivo following Prg4 inactivation, and B) dysregulation of Prg4 signaling was associated with high-grade synovitis." (PMID 41282165, 2025). "Dysfunction in PRG4 signaling, demonstrated by lower tissue levels of PRG4 along with higher CD44, XO and HIF-1α, was associated with high-grade synovitis." (PMID 41282165, 2025). "Mean CD44 staining intensity was higher in high-grade synovitis compared to corresponding mean intensity in low-grade synovitis (p < 0.001)." (PMID 41282165, 2025). "Interestingly, the enhancement in CD44 expression was directly related to synovitis grade, where high-grade synovitis tissues exhibited higher CD44 expression compared to tissues with low or no inflammation." (PMID 41282165, 2025). "Overall, high-grade synovitis specimens were more likely to have lower PRG4 content, along with higher CD44, XO and HIF-1α contents compared to low-grade synovitis specimens." (PMID 41282165, 2025). "Supporting this involvement is that the expression of XO and HIF-1α trended in the same direction as CD44, where in tissues with high-grade synovitis, we observed stronger XO and HIF-1α staining, while absent in normal tissues." (PMID 41282165, 2025). "We detected CD44 staining in low and high-grade synovitis specimens but not normal tissues." (PMID 41282165, 2025). "MPCs from all groups (normal versus ACL-I) and all grades of synovitis (ACL-I non-inflamed versus ACL-I inflamed) demonstrated robust expression of the typical MPC markers (CD105, CD90, CD73, CD44) and lacked the expression of hematopoietic lineage markers (CD45, CD11b)." (PMID 37357305, 2023).
thymoma (2 papers, 2020 to 2023). A neoplasm arising from the epithelial cells of the thymus. "In a preclinical study using a murine thymoma model, a comparative study between an anti-pan-CD44 mAb (IM-7) and an anti-murine CD44v10 mAb (K926) was conducted in CD44v10-transfected EL4 thymoma (EL4-v10)." (PMID 37504249, 2023).
upper tract urothelial carcinoma (2 papers, 2017 to 2024). "The aim of this study was to determine the association of basal compartment and superficial markers, comprising CK5/6, CD44, CK20, and the pathological characteristics of upper tract urothelial carcinoma (UTUC) associated with Balkan endemic nephropathy (BEN)." (PMID 38255201, 2024). "Tumor samples from 222 patients with upper tract urothelial carcinomas who were treated with radical nephroureterectomy were analyzed for the expression of seven basal/luminal immunohistochemical markers (CK5, EGFR, CD44, CK20, p63, GATA3, FOXA1)." (PMID 28632777, 2017).
Ureteral obstruction (2 papers, 2014 to 2016). Obstruction of the flow of urine through the ureter. "We also found that miR-328 expression decreased and CD44 increased in ureteric obstruction kidneys in the animal study." (PMID 24919189, 2014).
uterine fibroids (2 papers, 2021 to 2022). "In compliance with that, we showed that CD44/Stro1++ stem cells-derived UF organoids express an elevated level of POSTN compared to the MMSC-derived organoids suggesting that UFSC are predisposed to form uterine fibroids." (PMID 35585291, 2022). "The expression status of five biomarker candidate factors and CD44 was examined by molecular pathological analysis using IHC to understand the biological characteristics of intravenous leiomyomatosis obtained from a patient with uterine leiomyoma." (PMID 34563053, 2021). "Therefore, we examined the presence of CD44-positive cells in the internal tissue of intravenous leiomyomatosis using the excised tissue obtained from other patients with uterine leiomyoma." (PMID 34563053, 2021). "In the normal uterine leiomyoma, the expression of CD44 was not clearly observed." (PMID 34563053, 2021).
vaginal infection (2 papers, 2016 to 2025). "We detected variability in the expression of molecules involved in placental adhesion, angiogenesis, migration, differentiation, and immune modulation (VDR, CD44, OPN, and COX-2) in different pathogenic vaginal infections." (PMID 40243431, 2025). "Our results suggest that pregnant women have a 1.67 increased risk of experiencing a vaginal infection if they are CD44-negative, a 1.102 increased risk of experiencing a vaginal infection if they are VDR-negative, and a 2.933 increased risk of having a vaginal infection if they are OPN-positive." (PMID 40243431, 2025). "This research aimed to investigate how different types of vaginal infections during pregnancy alter the expression of VDR, CD44, OPN, and COX-2, thereby contributing to structural and functional changes in the placenta." (PMID 40243431, 2025). "VDR, CD44, and OPN had increased placental expression in GBS and Ureaplasma urealyticum vaginal infections; the opportunistic pathogenicity of both Escherichia coli and Candida spp." (PMID 40243431, 2025).
Vestibular schwannoma (2 papers, 2025). A vestibular schwannoma (also known as acoustic neuroma, acoustic neurinoma, or acoustic neurilemoma) is a benign, usually slow-growing tumor that develops from the VIIIth cranial nerve supplying the inner ear. "Our research demonstrated that the SPP1/CD44 pathway was activated in vestibular schwannoma tissues, aligning with findings from earlier studies." (PMID 40629113, 2025).